ENSG00000212517
Synonyms: LOC124900464
Gene: Small nucleolar RNA gene on chromosome 20 (5,121,417 to 5,121,539, reverse strand). Ensembl gene ENSG00000212517.
Gene Ontology:
Biological process: RNA processing
Cellular component: nucleolus
Homologues: Paralogues in human: SNORA26 (85% identical).